IL9 (interleukin 9)
Diseases named in the same sentence as IL9 in open-access papers (continued):
Sharing a sentence is not in itself a finding about the gene and the disease.
inflammation (20 papers, 2005 to 2025). Aberrant reaction of the microcirculation characterized by movement of fluid and leukocytes from the blood into extravascular tissues. "They showed that IL-9 treatment aggravates SARS-CoV-2-associated airway inflammation through the intranasal route for 24 h before euthanizing the mice." (PMID 38727220, 2024). "Other mediators, such as IL-5 (which promotes eosinophilic inflammation) and IL-9 (which stimulates the proliferation of mast cells), are also involved." (PMID 37513609, 2023). "The observed anti-inflammatory properties of IL9 overexpression are consistent with findings in IL9 knockout mice, in which its absence exacerbates cardiac inflammation and injury in VM18." (PMID 35508525, 2022). "IL-9 is a cytokine with pleiotropic function that mediates allergic inflammation and immunity to intestinal helminth parasites." (PMID 29872093, 2018). "Mice that received Th2 cells secreted IL-4, IL-5 and IL-9 and up-regulated Arg1, Eotaxin (Ccl11) and Gob5 (Clca3) within the lung, characteristic of Th1 or Th2-mediated airway inflammation." (PMID 23825948, 2013). "Selective overexpression of the IL-9 gene in the airways of transgenic mice resulted in massive airway inflammation, with infiltration of eosinophils and lymphocytes, mast cell hyperplasia, and increased subepithelial collagen deposition." (PMID 20976014, 2010). "We aimed to evaluate the therapeutic effect of a neutralizing anti-IL-9 antibody in a mouse model of airway eosinophilic inflammation and compared any such effect with anti-IL-5 treatment." (PMID 15823208, 2005). "Considering the set of results, we can hypothesize that P2Et treatment decreases lung inflammation by the modulation of the IL-33-ILC2-Eosino-IL-9 axis in early timepoints, but also trough the effect on innate immune populations." (PMID 36160152, 2022). "Interestingly, augmented IL9 along with low CD96 and DPP4 expression observed in UC relative to CD mimics a Th9 pro-inflammatory profile associated with chronic intestinal inflammation in mice." (PMID 31191543, 2019). "IL-9 production by a subset of non-invariant (type 2) murine CD1d-restricted CD4+ NKT cells is associated with IgE production and antigen-induced pulmonary inflammation and mast cell infiltration." (PMID 22174854, 2011).
immune dysfunction (6 papers, 2013 to 2025). "CD is characterized as a Th1-mediated inflammatory response with overproduction of interferon-γ (IFN-γ) and TNF-α whereas UC is considered a Th2-mediated immune disease with massive production of interleukin IL-4, IL-5, IL-9, and IL-13." (PMID 30150894, 2018). "Additionally, multiplex cytokine analysis revealed significant elevations in Eotaxin, IL-1β, IL-4, IL-6, IL-8, MIP-1α, and TNF-α in SZ patients, whereas IFN-γ, IL-9, IL-1ra, IL-13, MCP-1, MIP-1β, and RANTES were reduced (p < 0.05), indicating a complex immune dysfunction associated with SZ." (PMID 40761785, 2025).
bacterial infections (5 papers, 2015 to 2025). "This modulation of immunity is also supported by decreased levels of cytokines responsible for controlling bacterial infections, such as IL-1β, IL-6, IL-9, IL-12, TNF-α, IL-17, and IFN-γ, observed in the serum of the WT mice." (PMID 32139610, 2020). "To date, the study on the role of IL-9 in bacterial infections is limited and the reported data are contradictory." (PMID 25646821, 2015).
cerebral artery (4 papers, 2022 to 2024). "The pSTAT3/SOCS3 axis is markedly altered during colorectal tumorigenesis and might be a target for IL-9-dependent regulation of epithelial cell proliferation." (PMID 35793807, 2022).
hematological malignancies (4 papers, 2014 to 2021). "Although interleukin-9 (IL-9) exhibits pleiotropic functions in the immune system, it remains a well-known cytokine in hematological malignancies." (PMID 24520283, 2014). "In any case, the role of IL-9 and STATs has important implications for pathophysiology and treatment in hematological malignancies." (PMID 24520283, 2014). "IL-9 also participates in the pathogenesis of T cell hematologic malignancies." (PMID 34944921, 2021). "Up to now, no direct evidence has been observed to prove that IL-9 in hematological malignancies was derived from Th9 cells and the underlying mechanisms of IL-9 in various hematological malignancies development need to be further explored." (PMID 32508847, 2020). "Besides the role of IL-9 during immune responses, its growth factor and antiapoptotic activities on multiple transformed cells suggest a potential role in hematological malignancies." (PMID 24520283, 2014). "Previous cell culture and animal model studies have revealed that the Janus kinase-signal transducer and activator of transcription signaling pathway, which may be activated by a number of cytokines including IL-9, is critical in hematological malignancies." (PMID 24520283, 2014).
kidney diseases (4 papers, 2020 to 2025). "The rationale was based on recent studies that revealed a protective effect of IL-9 on glomerular podocyte injury in experimental kidney disease." (PMID 35445345, 2022). "In a recent study of experimental murine kidney disease, Xiong and coworkers reported that intra-renal IL-9 attenuated podocyte injury in mice with adriamycin-induced nephropathy." (PMID 35445345, 2022). "The impact of IL-9 on podocyte injury in human kidney disease remains largely unexplored." (PMID 35445345, 2022). "Thus, the inhibition of H3K27 acetylation may orchestrate the expression of IL-9 in kidney diseases." (PMID 32194547, 2020). "The increase in IL-9 in DKD also coincided with rising TGF-β levels and declining IL-17 expression, pointing to a potential compensatory or protective role in later stages of kidney disease." (PMID 40804870, 2025). "Thus, our findings indicate novel and potent anti-inflammatory properties of IL-9 that confer preservation of kidney function and structure in CP-induced AKI, which may counteract kidney disease procession." (PMID 32194547, 2020).
hematological cancers (3 papers, 2017 to 2023). "It needs further investigation whether high expression of IL-9 is involved in protecting T cell-derived hematological cancer cells from ferroptosis." (PMID 38288118, 2023).
infectious disease (3 papers, 2011 to 2025). A disorder directly resulting from the presence and activity of a microbial, viral, or parasitic agent in humans. "IL-9 is mainly generated by CD4 + cells which have been shown to be involved in infectious diseases, such as clearance of respiratory syncytial virus." (PMID 38229040, 2024).
intestinal disease (3 papers, 2023 to 2024). "Thus, we demonstrate that an extra-intestinal disease can trigger an ILC2/IL-9 immune circuit, which induces PCM and regulates epithelial cell fate decisions in the GI tract." (PMID 38042840, 2023).
cardiovascular disease (2 papers, 2013 to 2022). "However, the role of IL-9 in cardiovascular disorders is largely unknown." (PMID 24023645, 2013).
connective tissue disease (2 papers, 2017). "IL-9 and Th9 cells are increased in subjects with inflammatory arthritis, connective tissue diseases, autoimmune colitis, and autoimmune encephalomyelitis." (PMID 29023386, 2017).
hematological neoplasms (2 papers, 2020 to 2024). "As a lymphocyte growth factor, IL-9 can promote the proliferation and activation of lymphocytes, so in most of the hematological tumors, it exerts a tumorigenic role." (PMID 32228589, 2020).
metabolic disease (2 papers, 2025). A congenital disorder (due to inherited enzyme abnormality) or acquired (due to failure of a metabolically important organ) disorder resulting from an abnormal metabolic process. "Similarly, PPAR-γ agonists used clinically for metabolic disorders can suppress IL-9 production, but may cause adverse effects including weight gain, fluid retention, and bone loss." (PMID 41030439, 2025).
adenocarcinoma (1 paper, 2006). A common cancer characterized by the presence of malignant glandular cells. "However, IL9 expression was relatively uncommon in adenocarcinoma compared with PMP tissue (P=0.009)." (PMID 17031402, 2006). "Interleukin-9, which induces MUC-2 and MUC-5AC gene expression in the lung, and its receptor, IL-9Rα, were expressed at variable levels in all cases of PMP with increased IL-9 expression in the epithelial PMP cells compared with adenocarcinoma." (PMID 17031402, 2006). "Similarly, expressions of mucin-related proteins were comparable for adenocarcinoma and PMP, with the exception that IL-9 expression was uncommon in adenocarcinoma (P=0.009)." (PMID 17031402, 2006).
benign neoplasm (1 paper, 2015). A neoplasm which is characterized by the absence of morphologic features associated with malignancy (severe cytologic atypia, tumor cell necrosis, and high mitotic rate). "We found that Th9 cells and IL-9 were involved in the pathogenesis of REAH, further confirming that the inflammatory response may play a central role in its development, thus negating the theory that REAH is a benign neoplasm." (PMID 26131817, 2015).
IL9 also shares sentences with these, for which no sentence is quoted: psoriasis vulgaris (5 papers); Alzheimer disease (4); intestinal inflammation (4); pneumonia (4); Anxiety (3); idiopathic pulmonary fibrosis (3); peanut allergy (3); pulmonary hypertension (3); acute tubular necrosis (2); Behçet disease (2); bipolar disorder (2); cardiac disease (2); cardiomyopathy (2); celiac disease (2); chronic hepatitis B (2); chronic hepatitis C (2); chronic periodontitis (2); contact dermatitis (2); Eczema (2); hyperlipidemia (2); immunodeficiencies (2); liver cirrhosis (2); migraine (2); myasthenia gravis (2); respiratory diseases (2); sarcoidosis (2); Achalasia (1); acute pancreatitis (1); adenoma (1); Airway obstruction (1).
A further 86 diseases each share a sentence with IL9 in 1 paper.